MIR1180 (microRNA 1180)
Synonyms: hsa-mir-1180; MIRN1180; mir-1180
Gene: MicroRNA gene on chromosome 17 (19,344,506 to 19,344,574, reverse strand). Ensembl gene ENSG00000221540.
Gene Ontology:
Biological process: miRNA-mediated post-transcriptional gene silencing
Cellular component: RISC complex
Homologues: Orthologues: chimpanzee MIR1180 (96% identical), macaque mml-mir-1180 (81% identical).